IL1B (interleukin 1 beta)
Diseases named in the same sentence as IL1B in open-access papers (continued):
Sharing a sentence is not in itself a finding about the gene and the disease.
dental caries (8 papers, 2011 to 2025). The decay of a tooth, in which it becomes softened, discolored, and/or porous. "Our study revealed a significant increase in IL-1β levels in saliva of smokers with dental caries, and a positive association between IL-1β levels and caries disease." (PMID 37224312, 2023). "The objective of this study was to assess the levels of secretory IgA (s-IgA) and IL-1β in the saliva of smokers with dental caries, and to discover the correlation between these parameters and dental caries." (PMID 37224312, 2023). "The results of our current study suggest a link between the production of inflammatory and immunoregulatory cytokines represented by IL-1β in smokers with dental caries, so this parameter can be used as an important biomarker to indicate the disease severity and progression." (PMID 37224312, 2023). "Salivary IgA and IL-1β in smokers with dental caries and healthy group." (PMID 37224312, 2023). "A positive association was observed between an elevated IL-1β level and dental caries, while there was no positive association between increased levels of IgA and dental caries." (PMID 37224312, 2023). "In the background of dental caries, the effects of several cytokines have been hypothesized, in which IL-1β and TNFα play a central role, because their up-regulation was demonstrated in the odontoblast layer on the surface of carious teeth by in vitro and in vivo experiments." (PMID 38334643, 2024). "There are seven key proteins involved in the action of curcumin on dental caries: MAPK1, BCL2, KRAS, CXCL8, TGFB1, MMP9, and IL1B, all of which spontaneously bind curcumin." (PMID 38920854, 2024). "The mean saliva IgA levels between smokers with dental caries group and healthy subjects were not significantly different (p=0.077), while the saliva levels of IL-1β were higher in the smokers in dental caries group, with a significant difference of p<0.05." (PMID 37224312, 2023). "Correlation between salivary IgA, IL-1β, CRP, BMI, age, and sex insmokers with dental caries." (PMID 37224312, 2023). "A distinct bacterial community structure and a differential expression of innate immune responses were observed in dental caries of Mexican individuals, with 2 genera, Olsenella and Parascardovia, exclusively found in moderate caries, and IL1β, IL6 and CXCL8 being overexpressed in dental caries." (PMID 36569197, 2022).
diabetic foot ulcers (8 papers, 2021 to 2025). "Persistently elevated levels of proinflammatory cytokines such as IL-6, IL-1β, IL-8 and TNFα have been found in the wound bed fluids of patients with diabetic foot ulcers." (PMID 39941031, 2025). "Contrary to our findings in acute diabetic wounds, there is evidence that IL-1β levels are increased in chronic diabetic wounds such as human diabetic foot ulcers, where it inhibits the healing process." (PMID 38373910, 2024). "A previous study showed that the wound healing rate can be accelerated through the marked downregulation of IL-1β in diabetic foot ulcer rats." (PMID 35069970, 2022). "In addition, TNF-α, IL-6, and IL-1β levels have been revealed to return to normal levels by propolis administration, and infections in diabetic foot ulcers have been proven to improve." (PMID 37542207, 2023). "In diabetic foot ulcers (DFU), the release of IL-1β and TNF-α by numerous M1 macrophages inhibits keratinocyte migration, thereby delaying wound healing." (PMID 41465092, 2025). "Real-Time Polymerase Chain Reaction: RT-PCR for the gene expression of CD68, CD86, CD206, CD40, IL-6, IL-1β, and TNF-α revealed increased relative gene expression (normalized to housekeeping gene 18S) in diabetic foot ulcer tissues compared to control tissues." (PMID 36362563, 2022).
endophthalmitis (8 papers, 2015 to 2024). An infectious process affecting the internal structures of the eye. "Compared to other inflammatory cytokines implicated in endophthalmitis, the expression and release of bioactive IL-1β are tightly regulated and require at least two distinct stimuli." (PMID 26865111, 2016). "In the current study, we demonstrated the ability of α-toxin to induce the inflammatory response, particularly via IL-1β, indicating another role of α-toxin in increasing the virulence of S. aureus in endophthalmitis." (PMID 26053426, 2015). "In the vitreous of patients with distinct clinical characteristics, an intensified inflammatory response involving IL-10, IL-6, IL-8, IL-1β, and TNF-α was observed in cases of MDR P. aeruginosa endophthalmitis compared to infections caused by sensitive P. aeruginosa." (PMID 37624004, 2023). "The cytokine milieu in endophthalmitis was characterized by innate-related IL-6, tumor necrosis factor (TNF)-α, and IL-1β, which are involved in ocular barrier breakdown and leukocyte recruitment into ocular tissue." (PMID 34783307, 2021). "Our results demonstrated elevated expression of 16 mediators such as GCSF, GRO, IFN-γ, IL-1α, IL-1β, IL-1 RA, IL-6, IL-8, IP-10, MCP-1, MCP-3, MIP-1α, IL-1β, TGF-α, TNF-α in patients with culture positive endophthalmitis." (PMID 30296277, 2018). "In an intradermal infection mice model, IL-1β, IL-6, TNF-α, and IFN-γ were produced by the lymph nodes only after MSSA infection; while in a murine model of endophthalmitis, IL-10, IL-15, IL-11, and some chemokines and receptors were significantly strongly upregulated by MRSA." (PMID 38571946, 2024). "Moreover, as neutrophils and retinal microglia-driven NLRP3 activation and IL-1β production play an essential role in murine bacterial endophthalmitis, 3K3A-APC treatment should be considered as a potential treatment for devastating, uncontrolled endophthalmitis." (PMID 36430674, 2022).
hepatitis C (8 papers, 2013 to 2024). "A recent study evaluated 201 Egyptian hepatitis C patients and found that the IL1B rs1143629 located in intron A/A genotype was prevalent in HCV patients [OR = 1.7 (95% CI = 1–2.8)]." (PMID 34161370, 2021). "Gene-gene interaction showed that individuals heterozygotes for both CARD8 rs2009373 and IL1B rs16944 are less prone to hepatitis C development (padj = 0.039)." (PMID 34161370, 2021). "Similar pattern was observed in patients with hepatitis C, mean circulating IL-1β levels were 21,96 ± 4.5 and 10,62 ± 3.3pg/mL among the C/C and G/G genotypes, respectively." (PMID 34161370, 2021). "Gene-gene interaction showed that individuals heterogyzotes for both CARD8-rs2009373 and IL1B-rs16944 are less prone to hepatitis C development (padj = 0.039)." (PMID 34161370, 2021). "The levels of IL-1β, IL-8 and TGF-β tend to be more severe hepatitis C, along with correlated positive results of TGF-β, TNF-α, IL-1β and IL-8." (PMID 39608222, 2024). "In the present study, we analyzed whether polymorphisms in inflammasomes genes IL1B rs16944, IL18 rs187238, NLRP3 rs10754558, CARD8 rs2009373, CTSB rs1692816 and AIM2 rs1103577 are associated with susceptibility to HCV infection and liver fibrosis in hepatitis C patients in the Amazon population." (PMID 34161370, 2021). "Diverse pro-inflammatory cytokines, such as IFN-α, TNF-α, IL-1β, or IFN-γ induce sphingolipid metabolizing enzymes and especially IFN-α has already been shown to effect a decrease, for example, in HDL cholesterol in hepatitis C patients treated with IFN-α." (PMID 27857690, 2016).
hyperferritinemia (8 papers, 2012 to 2025). "IL-1β drives hyperferritinemia, a hallmark of MAS, leading to prolonged macrophage activation and tissue damage." (PMID 40385895, 2025). "From a pathophysiologic standpoint, our patient’s striking hyperferritinemia and systemic inflammation reflect the central role of cytokine dysregulation, particularly IL-1β, IL-6, and IL-18, which drive the clinical phenotype and systemic inflammation." (PMID 41384165, 2025). "The pathogenesis of hyperferritinemia is thought to be cytokine-mediated, with interleukin (IL)1a, IL1b, IL6, IL18, tumor necrosis factor-a, c-interferon, and macrophage-colony stimulating factor all implicated." (PMID 36425471, 2022). "From this, we infer that IL-1β inhibition by Anakinra might decrease hyperferritinemia and MAS." (PMID 37674218, 2023). "Regulation by proinflammatory cytokines such as interleukin (IL)-1b, IL-6, IL-18, MCSF, and INF-α provides a link to the disease pathogenesis and may explain rapid resolution of hyperferritinemia after targeted treatment and inhibition of key cytokines." (PMID 22536541, 2012).
Hyperkeratosis (8 papers, 2013 to 2026). Hyperkeratosis is a histopathological term defining a thickened stratum corneum and may be present in many different skin conditions, with many possible overlaps. "Histopathological evaluation further revealed that mice receiving supplemental IL-1β exhibited sustained hyperkeratosis, acanthosis, and prominent perivascular inflammatory cell infiltration in the dermis compared to the brusatol-only group." (PMID 41508030, 2026). "We observed a significant increase in inflammatory factors (such as TNF-α, IL-1β, CXCL1, CXCL2, CCL4, and TLR7) and exacerbates hyperkeratosis and keratosis in STAT3 mice." (PMID 37465147, 2023). "The skin inflammation and hyperkeratosis from UVB irradiation in the Nlrp1b KI mice were inhibited by both intraperitoneal and subcutaneous administration of anti-IL-1β antibodies before UVB irradiation." (PMID 35784371, 2022). "IL-1β and IL-6 have been confirmed to promote the differentiation of CD4+T cells into Th17 cells, in which IL-17 is produced, and higher IL-17 levels recognized by keratinocytes leads to severe hyperkeratosis and inflammatory infiltration." (PMID 37111171, 2023).
hypertriglyceridemia (8 papers, 2018 to 2024). A laboratory test result indicating elevated triglyceride concentration in the blood. "Taken together, we conclude that the atheroprotective effect of Maxadilan is mainly downstream of cholesterol-induced inflammation, such as induction of TNF-α and IL-1β and, in addition, may involve activation of vasoprotective signaling, reduction of apoptosis, and hypertriglyceridemia." (PMID 39769009, 2024). "Already in the 1990s, two studies observed induction of hypertriglyceridemia upon LPS, TNF, or IL-1β exposure in rodents." (PMID 36672634, 2023). "Hypertriglyceridemia may result from excess glucose consumption, and it has been reported that the rate of TG and fatty acid clearance is suppressed by cytokines, notably TNF-α, IL-6, and IL-1β, increasing this condition, as our data show." (PMID 39452936, 2024). "In animal experiments, the ORG mice developed proteinuria, podocyte injury, and hypertriglyceridemia, accompanied with deregulated lipid metabolism, renal ectopic lipid deposition, activation of NOD-like receptor protein 3 (NLRP3) inflammasome, and secretion of IL-1β of the kidney." (PMID 31097920, 2019).
IgA nephropathy (8 papers, 2017 to 2025). "Furthermore, in patients, IL-1β plays a pathogenic role in the evolution of IgA nephropathy, and serum levels of IL 18 are elevated in IgA nephropathy patients." (PMID 39544933, 2024). "IL1B is produced locally in the glomeruli and mesenchyme in IgA nephropathy, leading to ongoing renal injury." (PMID 39492771, 2025). "Il-1β is also produced by several cell types during IgA nephropathy and promotes inflammation and disease progression." (PMID 35806457, 2022). "We have previously showed that IL-1β is involved in the pathogenesis of both spontaneously occurring and passively induced IgA nephropathy (IgAN) models." (PMID 28117341, 2017). "In patients with IgA nephropathy, circulating levels of NLRP3 inflammasome-derived cytokines, notably interleukin-18 (IL-18) and interleukin-1β (IL-1β), are significantly elevated, underscoring the inflammasome’s central role in disease progression." (PMID 41357229, 2025). "The CP improved kidney inflammation and fibrosis in IgA nephropathy rat models by reducing MCP-1, TNF-α, IL-1β, and IL-6 levels." (PMID 33806085, 2021).
inflammatory bone diseases (8 papers, 2015 to 2025). "Cytokine profiling showed that crude venom and HMM suppressed osteoclastogenic cytokines such as IL-1β and IL-6, supporting their potential use in inflammatory bone diseases." (PMID 40711169, 2025). "The combination of vancomycin treatment and HBO therapy did not lead to a significant reduction of the bacterial load, the histo-pathologically evaluated degree of osteitis and IL-1b, IL-10, and TNF-a levels, in comparison to vancomycin treatment alone." (PMID 29377928, 2018). "Like many chronic inflammatory states in the bone microenvironment, TLR4 activation plays a crucial role in producing various pro-inflammatory cytokines such as TNF-α, IL-6, and IL-1β in macrophages, which stimulate OC formation and contribute to the pathology of inflammatory bone diseases." (PMID 37596575, 2023). "Therefore, IL-1β has become a focus of research due its potential as an attractive therapeutic target for inflammatory bone disorders." (PMID 26078980, 2015). "Moreover, the interaction among the transcription factor forkhead box O1 (FoxO1), Propionibacterium acnes, NLR family pyrin domain-containing protein 3 (NLRP3) inflammasomes, and IL-1β may contribute to the pathogenesis of osteitis." (PMID 41303152, 2025).
intrauterine growth restriction (8 papers, 2018 to 2024). "The purpose of this study was to determine the association of IL-33, ST2, IL-1β, and T. gondii infection in women with intrauterine growth restriction." (PMID 39065188, 2024). "In contrast, recent evidence suggests that the decreased abundance of Clostridium_sensu_stricto_1 in intrauterine growth restricted (IUGR) piglets is negatively correlated with plasma proinflammatory cytokine (IL-1β, TNF-α, and IFN-γ) levels." (PMID 35369472, 2022). "A significant interaction effect of intrauterine growth restriction and treatment on IL-1β (P = 0.002) and IL-6 (P = 0.02) production was confirmed by two-way ANOVA, indicating that these factors acted dependently." (PMID 30116155, 2018). "Moreover, the effects of intrauterine growth restriction (P < 0.001) and treatment (P < 0.001) on IL-1β secretion were also significant." (PMID 30116155, 2018). "The patients in the groups with and without anti-Toxoplasma antibodies and intrauterine growth restriction were positive, with higher concentration levels compared to IL1-β and ST2." (PMID 39065188, 2024). "However, scavenging excess ROS did not improve intrauterine growth retardation (IUGR), and elevated circulatory sFlt1, sEng, IL-1β, and TNFα levels in DEX rats." (PMID 37237853, 2023).
lipid metabolism disorders (8 papers, 2020 to 2025). "GSDF improves tissue inflammation in mice caused by lipid metabolism disorders by inhibiting the expression of IL-1β, TNF-α, and other cell proteins." (PMID 40428495, 2025). "Research has identified similarities in decreased cell function, mitochondrial dysfunction, lipid metabolism disorders, chronic inflammation, and the role of pro-inflammatory cytokines like IL-1β and TNFα." (PMID 39176085, 2024). "GSDF increased the expression levels of PPAR-γ, AMPK, and P-AMPK proteins, and lowered the expression of IL-1β, TNF-α, and other proteins in the adipose tissues of the epididymis, in turn inhibiting adipogenesis and ameliorating lipid metabolism disorders." (PMID 40428495, 2025). "Network pharmacology analysis identified TNF-α, IL-18, IL-1β and PPAR-γ as major targets of LPQ1 in lipid metabolism disorders." (PMID 40730505, 2025). "This study has demonstrated the increased inflammatory factors (IL-1β and TNF-α) and concluded that the inflammation may play a regulatory role in lipid metabolic disorders induced by DEHP." (PMID 31979393, 2020).
measles (8 papers, 2013 to 2025). A highly contagious viral infection caused by the measles virus. "In the cases of RNA viruses, including influenza A, measles, and coronavirus disease, downregulation of genes such as Ddx58, Il1b, Stat1, Stat2, Oas3, Oas2, Oas1a, Oas1g contributes to increased susceptibility to infections." (PMID 40206211, 2025). "Those T-cells were co-cultured for 3 days with measles primed DCs exposed to combinations of IFNβ, TNFα and IL1β." (PMID 24616721, 2014). "Transcriptomic analysis of peripheral blood mononuclear cells (PBMCs) from children with measles shows upregulation of mRNAs for IL-1β, CIAS-1/NLRP3, tumor necrosis factor (TNF)α, CCL4/MIP-1β, CXCL2/GRO-β, CXCL8, and TNFAIP3/A20 consistent with NF-κB signaling and inflammasome priming." (PMID 36851476, 2023). "In order to see if the induction of the costimulatory markers by the triple combination of IFNβ, TNFα, and IL1β has an effect on T-cell activation, we studied the induction of measles specific T-cell proliferation after co-culture with cytokine pretreated and measles primed T-cells." (PMID 24616721, 2014). "The activation scores for TLR, NLR, cytokine-cytokine receptor, and TNF-α pathways, but not RLR, IL-1β, and measles pathways, were significantly upregulated in FSGS." (PMID 38127456, 2024). "Thus, upregulated SH3BP2, TNF-α, TLR, NLR, and cytokine-cytokine receptor pathway scores and unchanged scores for measles, RLR, and IL-1β pathways in human nephrotic syndrome indicate an important role of SH3BP2-mediated innate immune activation." (PMID 38127456, 2024). "However, MeV-induced innate responses likely influence the adaptive responses to infection that lead to virus clearance and protective immunity as IL-18 and IL-1β influence the CD4 and CD8 T cell differentiation phenotypes that characterize recovery from measles." (PMID 36851476, 2023).
myeloid leukemia (8 papers, 2012 to 2023). A clonal proliferation of myeloid cells and their precursors in the bone marrow, peripheral blood, and spleen. "We found a myeloid leukemia signature was also enriched in Tet2-KO HSCs relative to WT at steady state and upon IL1β stimulation." (PMID 38062031, 2023). "In agreement with our observations in mice, patient-derived myeloid leukemia cells exhibit KRAS/RAC1/ROS/NLRP3/IL-1β axis activity." (PMID 32246016, 2020). "The evidence supports the theory that dust particles can activate IL-1β, IL-16, NF-κB, and COX-2 expression in human myeloid leukemia cells, indicating strong inflammatory responses." (PMID 35723329, 2022). "Further, rFIP-mco can significantly reduce the expression levels of TNF-α, IL-1β, and IL-6 in the THP1 cells (human myeloid leukemia mononuclear cells)." (PMID 33193329, 2020).